KRAS (KRas proto-oncogene, GTPase)
Diseases named in the same sentence as KRAS in open-access papers (continued):
Sharing a sentence is not in itself a finding about the gene and the disease.
adenoma (continued). "Several expansions are attributed to adenoma mutations, with an interesting increase in the wild-type version of KRAS (pink line) following the first adenoma expansion (light green line)." (PMID 39593869, 2024). "KRAS mutation results in continuous activation of pathways promoting cell growth and survival, leading to the transition from adenoma to carcinoma." (PMID 39273409, 2024). "Most biomarkers for the outcome of adenocarcinoma used in histology are related to the adenoma-carcinoma pathway and show mutations in oncogenes such as KRAS, NRAS, BRAF, APC, and DDF." (PMID 38187473, 2023). "In colorectal adenomas, occurrence of a KRAS mutation on top of WNT signal-activating mutations was associated with the transition of small to large adenomas." (PMID 37643866, 2023). "APC mutated small adenomas have a slow growth rate, but further mutations of the KRAS gene can increase their proliferation." (PMID 37538108, 2023). "Among KRAS variants, codons 12 and 13 were the most frequent in our samples, with G12V dominance in adenomas and G12D in CRC cases." (PMID 36765865, 2023). "Mutation in KRAS is proposed to drive the progression of a small adenoma to a large adenoma before further genetic alterations result in the development of carcinoma and its progression." (PMID 36899966, 2023). "Women were also found to have KRAS mutations in codon 12 more frequently than men, which are associated with more advanced adenomas." (PMID 37348877, 2023). "In the adenoma group, the KRAS mutation frequency is within the variation observed in other studies (10.7% to 60.0%)." (PMID 35761395, 2022). "The incidence of KRAS mutation was reported to range from 13.6–35.0% and from 30–50% in adenomas and carcinomas, respectively." (PMID 36083889, 2022). "After the normal mucosal epithelium turned into an early adenoma, KRAS mutation occurred subsequently triggering early to intermediate adenoma." (PMID 35709138, 2022). "Although BCL6-deficient mice expressing oncogenic KRAS still developed lung hyperplasia or adenoma, a dramatically reduced tumor incidence was observed upon heterozygous or homozygous loss of BCL6 in the lungs." (PMID 36377663, 2022). "We found 33.3% of our samples harboring mutations in this pathway, with mutations in the KRAS gene slightly more frequent in the adenoma group (22.4%) and BRAF predominantly present in the SSL group." (PMID 35761395, 2022). "For the KRAS gene, several missense mutations were successfully identified in 34 individuals [24 individuals with either low- or high-grade adenoma and 10 with in situ carcinoma,] at codon 12: c.34G > C/A/T, c.35G > A/T/C, codon 13: c.38G > A/C/T, codon 61: c." (PMID 35173208, 2022). "The cases with an adenoma component had a 35.7% discordance rate on the KRAS mutation tests in their adenoma and carcinoma regions." (PMID 36083889, 2022). "In a molecular aspect, cases with a residual adenoma component revealed frequent KRAS mutation (65%) and the discordance of KRAS mutation test between adenoma and invasive carcinoma area was found in 35.7%." (PMID 36083889, 2022). "Studies report that oncogene-induced senescence (OIS) prevents progression of benign KRAS-mutated sessile serrated adenomas to invasive carcinomas and provides an important barrier opposing malignancy in these early lesions." (PMID 35492321, 2022). "Advanced adenomas had a significantly higher frequency of mutation in KRAS and a high overall mutation rate than early adenomas (92.9% vs. 59%, p = 0.006)." (PMID 35761395, 2022). "Discordance in the KRAS mutation results between the adenoma and carcinoma areas was identified in 5 of 14 cases (35.7%)." (PMID 36083889, 2022).
adenoma (continued). "On the way to the transformation from anormal colon epithelial cells to cancer cells, KRAS mutations occur, leading to the transformation from a small to a large adenoma." (PMID 35884381, 2022). "We analyzed 20 genes related to gastric tumors and polyps through next-generation gene sequencing (NGS) and found APC and KRAS gene mutations in the adenoma tissue." (PMID 35508985, 2022). "We also observed a higher frequency of mutations in the KRAS gene in advanced adenomas than in early adenomas, similar to previous studies, including reports on the Brazilian population." (PMID 35761395, 2022). "When comparing early and advanced adenomas, a higher frequency of mutations in KRAS was observed in the late stage of the lesion (p = 0.001)." (PMID 35761395, 2022). "For the Brazilian population, previous reports on the frequency of KRAS mutation in adenomas have reported a lower frequency than we found (13.6%)." (PMID 35761395, 2022). "The genetic sequence dysregulation begins in the intestinal epithelial stem cells by an inactivating mutation of APC allowing the formation of a small adenoma, follows by activation of oncogenes such as KRAS, initiating cancer cell expansion." (PMID 33916891, 2021). "KRAS mutations were found in most of the adenomas analyzed (62.4% of cases), particularly in pre-malignant and high-grade dysplasia adenomas." (PMID 33923068, 2021). "Subsequent mutations in the proto-oncogene KRAS are often seen at the early adenoma stage of CRC development." (PMID 33606788, 2021). "Accordingly, Luo and colleagues, in a comprehensive methylome analysis of CRC progression, demonstrated that only a subset of high frequency CpG site methylated adenomas showed KRAS mutations." (PMID 34372923, 2021). "Ahadova and colleagues found that somatic mutations in APC and KRAS genes were mainly associated with MMR-D adenomas in LS patients." (PMID 33923068, 2021). "Genetic features show that adenomatous polyposis coli gene mutations are present in the early phase of CRC formation in approximately 70% of adenomas, with 49–50% caused by KRAS mutations." (PMID 34444406, 2021). "Multiple somatic inactivating mutations in the APC and KRAS genes have also been found in a study on 37 FAP-derived adenomas." (PMID 33923068, 2021). "KRAS mutation made the adenoma canceration by dysregulating the activities of many functions, implying KRAS mutation played a key role during transformation from adenoma to CRC." (PMID 32117908, 2020). "The probability of detecting cfDNA is low in early-stage CRC and many groups showed different results in terms of diagnostic value of total ctDNA levels or analysis of KRAS mutations in the plasma of patients with adenomas." (PMID 32380676, 2020). "KRAS mutations occur at a late stage in adenoma development and are a key element for mCRC development." (PMID 33183271, 2020). "Support for this comes from the observation that KRAS G12V mutation is less abundant in colorectal adenocarcinomas than adenomas and the inverse correlations observed between KRAS G12V MF and maximum tumor dimension for both colon and thyroid cancers." (PMID 31469467, 2020). "The MSI pathway can involve both serrated neoplasia or adenoma-carcinoma sequence, which is characterized by mutations in KRAS 10%, BRAF~70%, and mutations in mismatch repair genes for Lynch syndrome." (PMID 32676506, 2020).
adenoma (continued). "For example, 43% of adenoma components and 51% of carcinoma components from 70 tumor samples comprising both adenoma and carcinoma were positive for KRAS mutations, while 23% generated discordant results." (PMID 31781186, 2019). "On the other hand, traditional serrated adenomas are now known to be secondary to the KRAS gene mutation and can evolve through the classical adenoma-to-carcinoma transition." (PMID 30420877, 2018). "The simultaneous presence of multiple mutations in KRAS suggests tumor heterogeneity in early adenomas." (PMID 30166531, 2018). "Twenty‐two (33.8%) of the 62 patients with adenomas and 9/65 (13.8%) of those with hyperplastic or other non‐neoplastic lesions had KRAS mutations in their plasma." (PMID 29125240, 2018). "The majority of colon neoplastic lesions arise through the classical adenoma-carcinoma pathway associated with KRAS mutations and chromosomal instability." (PMID 30323897, 2018). "Multiregional sequencing confirmed widespread genetic heterogeneity in six adenoma samples, which affected known driver genes and confirmed the heterogeneous nature of KRAS mutations." (PMID 30166531, 2018). "The early gene mutations responsible for initial adenoma mutation are represented by APC mutations, and for adenoma enlargement by KRAS and BRAF mutations." (PMID 29652830, 2018). "Females were also found to have higher frequency of KRAS mutations in codon 12 than males, which again are associated with more advanced adenomas." (PMID 30236083, 2018). "In contrast, a slightly higher percentage of KRAS exon 2 mutations was detected in CD166-pac (22%: 11/49) than CD166-negative adenoma cells (CD166-nac) (17%: 4/23) in CAD." (PMID 29755662, 2018). "They originate from serial gene mutations, particularly the APC and KRAS genes, and are known as the classical adenoma-to-carcinoma sequence." (PMID 30420877, 2018). "DNA from 76 formalin-fixed, paraffin-embedded (FFPE) adenoma specimens, mostly low-grade and small lesions, was tested to identify mutations in KRAS and BRAF oncogenes." (PMID 30166531, 2018). "The genetic changes involve the initial loss or mutation of APC/β-catenin genes for the formation of aberrant crypts foci, mutations of KRAS/BRAF to advanced adenoma, and other acquired mutations for transformation to carcinoma." (PMID 29069792, 2017). "A recent report provided indirect evidence for our finding in that conventional adenomas which occur synchronously with SSA/P lack KRAS mutation which is a known feature of villous histology." (PMID 28424049, 2017). "In the univariate analysis, KRAS mutations were associated with the development of metachronous advanced polyps (OR: 2.36, 95% CI: 1.22–4.58; P = 0.011), and specifically, advanced adenomas (OR: 2.42, 95% CI: 1.13–5.21; P = 0.023)." (PMID 28953955, 2017).
adenoma (continued). "Traditional serrated adenomas, a type of premalignant precursor lesion, frequently (∼80%) have KRAS mutations or less often (20–30%) BRAF mutations and are MSS or MSI-low." (PMID 28740573, 2017). "The third is the alternative pathway, which starts from normal mucosa via villous, partly serrated adenomas (with KRAS, BRAF, and APC mutations and CIMP) and results in colon cancer with poor prognosis (with CIMP)." (PMID 26738600, 2016). "As observed in sporadic CRC and adenoma, intermediate-methylation epigenotype is accompanied with KRAS mutation and low-methylation epigenotype is accompanied with no oncogene mutation." (PMID 27563825, 2016). "We also found three adenomas carrying protein‐changing KRAS mutations; MAP polyp 1B4S carried a p.G12C, while FAP polyps 12A11S and 9A5S carried p.A146T and p.G13D changes, respectively." (PMID 26414517, 2016). "KRAS mutations presented in 40.9% of adenomas that were graded as having high-grade dysplasia, but only in 25.2% of adenomas with low-grade dysplasia." (PMID 26910894, 2016). "KRAS mutations were present in 38.8% of the adenomas that were tubulovillous or villous compared with 15.5% of adenomas that were of tubular histology." (PMID 26910894, 2016). "Of the 143 adenomas with KRAS mutations, 101 (70.6%) had a single mutation at codon 12; 30 (21.0%) had a single mutation at codon 13; and 12 (8.4%) had 2 different KRAS mutations." (PMID 26910894, 2016). "As detected in intermediate-methylation sporadic CRC, it suggested that methylation accumulation and KRAS-mutation(+) are mostly completed by the adenoma stage." (PMID 27563825, 2016). "Loss of function of APC tumor suppressor gene is thought to initiate neoplastic growth, and activating mutations of KRAS oncogene are commonly associated with tumor progression from a benign adenoma to a dysplastic adenocarcinoma." (PMID 27765040, 2016). "Analyses of different stages of human neoplasia and analyses of differently-sized adenomas revealed that KRAS mutations are rare (10%) in small and early adenomas but frequent (50%) in larger and more advanced adenomas." (PMID 26299805, 2015). "Although the KRAS mutation rate was minimal in the conventional adenoma cohorts, similarly low rates, particularly for TAs, have been previously found, and wide variations of KRAS mutation rates in adenomas have been reported." (PMID 25613750, 2015). "Mixed effects models revealed that mutations in APC, BRAF and KRAS occur at the transition from normal to adenoma stages whilst the hypermethylation of the Wnt antagonists continued to accumulate during the transitions from adenoma to carcinoma stages." (PMID 25432628, 2014). "Constitutive activation of Wnt/β‐catenin signaling initiates the growth of benign adenomas, while mutations in KRas, BRaf, and related pathways stimulate adenoma growth and contribute to invasive and other malignant behaviors." (PMID 24963032, 2014). "Of note, all of the adenomas analyzed exhibited APC inactivating mutations (exon 15) in combination with KRAS (G12D, G13D, Q61H) or BRAF (V600E) activating mutations." (PMID 23919615, 2013). "Subsequently, we compared the BRAF/KRAS mutational and the microsatellite stability status of the RCTs with the matched tubular adenomas (TAs) and normal mucosa." (PMID 23425390, 2013).
adenoma (continued). "In order to properly determine the timelines for CSMD1 and KRAS mutations, carful sequence analysis of early lesions such as adenomas will be required." (PMID 23505554, 2013). "KRAS mutations are thought to be related to the conversion of low-grade adenomas to high-grade adenomas, and also to protrusive growth." (PMID 23957258, 2013). "In contrast, traditional serrated adenomas are more often found in the distal colon, harbour KRAS mutations and are MSI-L or MSS." (PMID 23045412, 2012). "One of the polypoid adenomas with a c.1513C>T (p.R505C) FBXW7 mutation also harbors a KRAS mutation, (c.35G>A)." (PMID 22848674, 2012). "A KRAS codon 12 mutation (c.35G>T; p.G12V) was detected in the pyloric gland adenoma and in the adjacent dysplasia by sequencing analysis." (PMID 23206236, 2012). "The other three flat adenoma subtypes showed overall KRAS mutation rates of 26.8% (95% CI 14.22 to 42.94%), 26.73% (95% CI 14.16%-42.82%) and 34.67% (95% CI 15.58%-58.26%) for IIa, LST-F and LST-G, respectively." (PMID 22848674, 2012). "KRAS mutations have generally been considered to be characteristic of Vogelstein's adenoma–carcinoma model, and the integration of KRAS mutation in the model was justified by the high frequency of KRAS mutations in CRCs." (PMID 21457162, 2011). "KRAS mutations have been considered to be the hallmark mutations of Vogelstein's adenoma–carcinoma model." (PMID 21457162, 2011). "The serrated adenocarcinoma cases presenting with a residual adenoma component undoubtedly showed KRAS mutations (57.1%) to be twice as frequent as BRAF mutations (28.6%) in serrated adenocarcinomas." (PMID 21457162, 2011). "In this study KRAS mutation occurred with the same frequency in small (18%) and large (17%) adenomas but was significantly more frequent in adenomas that included a villous architecture (50%)." (PMID 16879389, 2006). "While the acquisition of KRAS mutation is also observed in adenomas, this change is correlated with the development of a villous architecture and in some cases the presence of epithelial serration (see Discussion of Group B serrated polyps above)." (PMID 16879389, 2006). "Accumulating genetic evidence supports a multistep model of tumor progression, in which early APC loss leads to chromosomal instability and adenoma formation, followed by activating mutations in KRAS that synergize with β-catenin signaling to promote tumor growth and invasion." (PMID 41294868, 2025). "An advanced adenoma arises from an adenoma as a consequence of an oncogenic KRAS driver mutation." (PMID 40075600, 2025). "Constitutive KRAS mutations, found in about 50% of all CRCs and in advanced adenomas, drive persistent activation of the RAF/MEK/ERK mitogen-activated protein kinase (MAPK) cascade and the PI3K/AKT pathway independently of upstream signals, including the epidermal growth factor receptor (EGFR)." (PMID 41294868, 2025).